SDC2 (syndecan 2)
Diseases named in the same sentence as SDC2 in open-access papers (continued):
Sharing a sentence is not in itself a finding about the gene and the disease.
colon carcinoma (continued). "Increased cell migration was seen with wild-type (MMP-7-cleavable) syndecan-2, whereas a protease-resistant mutant triggered far less migration in human colon cancer cell lines and an animal model." (PMID 25686828, 2015). "High syndecan-2 expression is related to tumorigenic behaviors through regulation of cell adhesion, proliferation, and migration in colon cancer cells." (PMID 25686828, 2015). "Together, these previous data support our contention that shed syndecan-2 plays a critical role in colon cancer cells." (PMID 25686828, 2015). "Of the four syndecan family members, syndecan-2 has been previously reported as up-regulated in several colon carcinoma cells and, further, that this increased expression is crucial for tumorigenicity." (PMID 23705906, 2013). "The increase of syndecan-2 expression in human colon cancer tissues has already been demonstrated, and our results showed that ECM proteins can be responsible for this augmentation." (PMID 23705906, 2013). "Many colon cancer cell lines show increased syndecan-2 expression, and this up-regulation seems to be crucial for their tumorigenic activity." (PMID 23705906, 2013). "In several tumors, including gastric and colon cancers, SDC2 was overexpressed." (PMID 39285301, 2024). "Previous studies have shown that SDC2 is highly expressed in colon cancer cell lines compared to normal cell lines and in cancer tissues compared to neighboring normal tissues, and that this plays an important role in regulating colon cancer activities." (PMID 35682569, 2022). "Thus, the SDC2–MMP-7 interaction appears to be important for the enzymatic activity of MMP-7 in colon cancer cells." (PMID 35682569, 2022). "Moreover, HT29-SDC2 cell showed increased cell surface localization of MMP-7, confirming that SDC2 regulates the cell surface localization of MMP-7 in colon cancer cells." (PMID 35682569, 2022). "Although future studies will be required to clarify the underlying inhibitory mechanism and improve the stability of these peptides before they can be developed as new anticancer drugs, the present study lays new groundwork for the specific targeting of MMP-7 via SDC2 in colon cancer." (PMID 35682569, 2022). "SDC2 can promote epithelial-mesenchymal transition in colon cancer." (PMID 34987579, 2021). "Indeed, SDC2 acts as a docking receptor for pro-MMP-7 in colon cancer cells, promoting pro-MMP-7 processing into the active MMP-7, and subsequent cleavage of MMP-7 substrate E-cadherin, which, in turn, results in enhanced cell migration." (PMID 32916872, 2020). "Therefore, in CRC, syndecan-2 plays a critical role in adhesion of colon carcinoma cells onto the ECM, regulating the proliferation and tumorigenic activity in colon carcinoma cells." (PMID 30027065, 2018). "Syndecan-2 is upregulated in breast tumors and in colon carcinomas." (PMID 26869927, 2016). "To directly assess the role of syndecan-2 extracellular domain shedding, we investigated whether shed syndecan-2 itself promotes colon cancer cell activities." (PMID 25686828, 2015). "We finally investigated how shed syndecan-2 regulates tumorigenic activity in colon cancer cells." (PMID 25686828, 2015). "Moreover, activated MMP-7 can enhance syndecan-2 extracellular shedding to produce the soluble form of syndecan-2 in colon cancer cell conditioned media." (PMID 25686828, 2015). "We suggest that anti-syndecan-2 antibody may provide a new therapeutic approach for diagnosis and treatment of colon cancer." (PMID 25686828, 2015). "Taken together, these results demonstrate that shed syndecan-2 directly enhances colon cancer progression and may be a promising therapeutic target for controlling colon cancer development." (PMID 25686828, 2015). "Syndecan-2 shedding plays a key role in promoting tumorigenic activities of colon cancer cells." (PMID 25686828, 2015).
colon carcinoma (continued). "ELISA assay with sera from the colon cancer patients revealed that levels of shed syndecan-2 in the sera were 625.9 ng/ml (range 321.2–863.6 ng/ml) in advanced colon cancer patients, whereas those of the sera from healthy people (N) was 176.3 ng/ml (range 87.4–431.0 ng/ml)." (PMID 25686828, 2015). "We subsequently investigated whether shed syndecan-2 accumulated in serum from patients with colon cancer." (PMID 25686828, 2015). "Colon cancer cell migration was increased in response to treatment with exogenous shed syndecan-2." (PMID 25686828, 2015). "In this study, we determined if shed syndecan-2 played a role in cancer regulation and if it could be used as a therapeutic biomarker for colon cancer." (PMID 25686828, 2015). "Moreover, studies to find specific strategies to disrupt the functions of shed syndecan-2 as a potential therapeutic approach for colon cancer also need to be continued." (PMID 25686828, 2015). "Interestingly, when both syndecans were coexpressed in colon cancer cells, the syndecan-2 mediated promigratory and adhesive effect was decreased by syndecan-4 and vice versa." (PMID 26378057, 2015). "We then determined if shed syndecan-2 in sera from colon cancer patients could be related with colon cancer activity." (PMID 25686828, 2015). "Treatment with exogenously shed syndecan-2 from HT29-cell-conditioned media enhanced the migration of HCT116 cells, suggesting that shed syndecan-2 may also regulate the tumorigenic characteristics of colon cancer cells in a paracrine manner." (PMID 25686828, 2015). "Notably, the present data show that syndecan-2 shedding is involved in the regulation of colon cancer cell migration." (PMID 25686828, 2015). "Two commercially available kits, the EarlyTect-Colon Cancer and Colosafe, which respectively received approval from the Korean Food and Drug Administration and the China National Medical Products Administration, have been designed to only detect methylated Syndecan2 (SDC2) genes." (PMID 37511475, 2023). "Interestingly, hetero-oligomerization with syndecan-2 reduces both syndecan-4-dependent PKCα activation and cell adhesion and syndecan-2-mediated migration and anchorage-independent growth in colon cancer cells, suggesting a functional interplay of syndecans in tumor progression." (PMID 33810567, 2021). "Since syndecan-2 plays an important role in regulating the tumorigenic activities of colon cancer cells, we next investigated whether the reduced activation ability of the Y51A mutant affected the tumorigenic activity of colon cancer cells." (PMID 31337828, 2019). "Since it is known that MMP-7 is localized at invasive front in colon cancer cells, syndecan-2 could immobilize pro-MMP-7 to restrict its range of action and regulate the processing of pro-MMP-7 to further regulate degradation of ECM and cell adhesion molecules." (PMID 31337828, 2019). "Indeed, shed syndecan-2 enhanced the tumorigenic characteristics of colon cancer cells in an autocrine manner, potentially affecting both the primary tumor growth and the metastatic ability of colon cancer cells." (PMID 25686828, 2015). "Because SDC-2 has been associated with tumorigenicity in sarcoma, fibrosarcoma, melanoma and colon cancer cells, we set out to determine whether modulation of SDC-2 expression in pancreatic cancer cells would affect their motility and their invasive capacity in vitro." (PMID 22471946, 2012). "Syndecan-2 enhances pro-MMP-7 processing and the subsequent cleavage of the E-cadherin substrate, enhancing colon cancer cell migration." (PMID 39153155, 2024). "In summary, we herein reveal that mimetic peptides derived from SDC2 (e.g., S2-FE) can interrupt the interaction of SDC2 with pro-MMP-7 and thus suppress colon cancer cell activities." (PMID 35682569, 2022).
colon carcinoma (continued). "Cologuard©, Epi proColon©, and EarlyTect© are non-invasive screening tests for colon cancer that are currently in use and rely on the methylation of genes such as BMP3, NDRG4, SEPT9, SDC2 for early detection." (PMID 35663592, 2021). "For example, syndecan-2 can regulate the localization and activation of matrix metalloproteinase (MMP)-7, which is overexpressed in colon cancer." (PMID 25686828, 2015). "It should be noted that SDC2 DNA methylation testing in stool samples is approved in Korea (EarlyTect-Colon Cancer) and China (Colosafe) for CRC detection, and a yet unapproved test described as ColoDefense includes screening for both SDC2 and SEPT9 DNA methylation." (PMID 37296894, 2023). "Furthermore, SDC2 enhances FAK phosphorylation and the downstream extracellular signal-regulated kinase (ERK) activity in colon cancer cells." (PMID 32916872, 2020). "We previously showed that syndecan-2 directly interacts with pro-MMP-7 and may contribute to processing it into active MMP-7 in colon cancer cells." (PMID 31337828, 2019). "Shed syndecan-2 was detected in 69% of advanced colon cancer patients (AC), but not in normal serum." (PMID 25686828, 2015). "Treatment with purified His-tagged syndecan-2 extracellular domain showed significant effects, on migration and anchorage-independent growth of colon cancer cells, without affecting cell proliferation." (PMID 25686828, 2015). "Compared to S2-P, S2-FE was better able to inhibit the SDC2–MMP-7 interaction, the cell surface localization of MMP-7, the gelatin degradation activity of MMP-7, and the cancer activities (cell migration, invasion, and colony-forming activity) of human HCT116 colon cancer cells in vitro." (PMID 35682569, 2022). "To determine whether extracellular shedding of syndecan-2 was necessary for syndecan-2-mediated functions in colon cancer, we constructed a non-cleavable mutant (NC) of rat syndecan-2 in which the Asn148-Leu149 residues were replaced with Asn148-Ile149." (PMID 25686828, 2015). "In contrast, colon cancer cell lines HT29, Caco-2 and DLD1 show low syndecan-2 expression, and inhibition of syndecan-2 function in these cell lines did not affect any of their adhesion, proliferation, invasion and migration." (PMID 23705906, 2013).
breast carcinoma (27 papers, 2008 to 2026). "Syndecan-2 is associated with tumor progression and invasiveness in several types of cancers, such as melanoma, fibrosarcoma, and breast cancer." (PMID 40076757, 2025). "Imatinib, an inhibitor of several tyrosine kinases, including BCR-ABL, c-KIT, and PDGF-Rs, significantly mitigated PDGF-induced breast cancer cell proliferation, invasiveness, and migratory capacity, associated with downregulation of SDC2 and 4 expressions." (PMID 36980680, 2023). "As expected, several of the genes associated with top differentially methylated probes between these groups have been previously implicated in breast cancer, including SDC2, PBK, ALOX12B, DAG1, ZNF382, and FST." (PMID 35564499, 2022). "Moreover, high SDC2 expression at the protein level was associated with worse OS in breast cancer patients with nLNM (P < 0.05, n = 93)." (PMID 40940401, 2025). "However, both nLNM and pLNM breast cancer patients with high expression of SDC2 mRNA and protein levels were associated with shorter OS." (PMID 40940401, 2025). "Pathways identified in CXCL12 and FB2 fibroblast cell clusters from RA and in the B2 cell cluster from HER2+ breast cancer patients support that TMEM230/RNASET2/SDC2/IRF1 axis have pleiotropic functions." (PMID 40862725, 2025). "In some biological settings, E2 is profibrotic; for instance, in dermal fibroblasts, E2 promotes fibrosis by inducing TGF-β1 and TGF-β2 expression, and in breast cancer cells, E2 increases syndecan-2 and MMP-9 expression through ERα signaling." (PMID 41533935, 2025). "The analysis demonstrated a significant downregulation of SDC2 mRNA expression in breast carcinoma tissues (P < 0.0001), whereas the SDC2 protein was found at higher levels in these cancer tissues compared to that found in normal tissues (P < 0.01)." (PMID 40940401, 2025). "We investigated SDC2 and FN mRNA expression in breast cancer according to nodal metastasis status and cancer staging using the UALCAN and cBioPortal online databases." (PMID 40940401, 2025). "In this study, we demonstrate elevated expression levels of SDC2 and FN in plasma-derived MV-enriched EVs isolated from neoadjuvant chemotherapy-naïve obese breast cancer patients with pLNM compared to those patients with nLNM." (PMID 40940401, 2025). "It has been shown that SDC2 expression is required to enhance growth and invasiveness of breast carcinoma cells by modulating cytoskeletal organization." (PMID 40940401, 2025). "The online bioinformatics tools and qPCR uncovered that SDC2 mRNA expression was significantly reduced in breast cancer tissues with pLNM and advanced stage compared to those with nLNM and normal tissues, respectively." (PMID 40940401, 2025). "In this study, we identified expression patterns of IRF1, TMEM230, RNASET2, and syndecan 2 (SDC2) in different cell types of breast cancer patients using single-cell mRNA transcript analyses." (PMID 40862725, 2025). "Future research is essential to unravel the molecular mechanisms driving the elevated levels of SDC2 and FN in MV-enriched EVs and their role in preparing the metastatic niche for breast cancer cells." (PMID 40940401, 2025). "The results indicated that breast cancer patients with pLNM who had lower levels of SDC2 mRNA expression experienced better OS (P < 0.05, n = 452)." (PMID 40940401, 2025). "Previous studies have documented a significant upregulation of SDC2 in breast cancer cell lines relative to healthy mammary cells." (PMID 40940401, 2025). "qRT-PCR was employed to quantify the transcript levels of SDC2 and FN in tumor tissue specimens from breast cancer patients with nLNM and pLNM." (PMID 40940401, 2025). "High mRNA levels of SDC2 showed shorter relapse-free survival (RFS) in all breast cancer patients (P < 0.05, n = 4929)." (PMID 40940401, 2025). "SDC2 has been demonstrated to contribute to cellular morphological changes, focal adhesions, and motility in breast cancer, ultimately inducing cell migration." (PMID 38472225, 2024).
breast carcinoma (continued). "In the context of the tumor microenvironment, SDC2 has been shown to be expressed on stromal cells within breast cancer tissue and positively modulates the transforming growth factor-β (TGF-β) signaling mainly through SMAD7, PAI-1, and CXCR4." (PMID 36980680, 2023). "Decreasing SDC2 expression led to cell cycle arrest and reduced the occurrence of cancers, such as colon and breast cancer." (PMID 37358427, 2023). "In malignant breast cancer cells, SDC2 interaction with β1 integrin promotes the invasive capacity of the cells by regulating the Rho GTPase activity." (PMID 32916872, 2020). "Soluble SDC1 promotes the growth of myeloma tumors in vivo, while shed SDC2 enhances colon, lung, and breast cancer progression." (PMID 32916872, 2020). "In ERα-positive breast cancer cells, expression levels of syndecan-2 are controlled through the EGFR signaling pathway, in contrast to syndecan-4 where the expression is regulated by IGF-IR signaling." (PMID 28079144, 2017). "As a whole the data suggest that syndecan-2 in breast carcinoma plays a major regulatory role in maintaining the invasive phenotype and appears to suppress the focal adhesion promoting role of syndecan-4." (PMID 25623282, 2015). "We also show that a heparan sulfate proteoglycan, syndecan-2 is a regulator of breast carcinoma invasiveness." (PMID 25623282, 2015). "The current data strongly suggest that syndecan-2 is a tumor promoter by regulating cytoskeletal organization and tumorigenic activity in breast cancer cells." (PMID 25623282, 2015). "The expression of SDC2 in breast cancer cells is regulated by estradiol (E2) through the action of estrogen receptor alpha (ERα)." (PMID 25140302, 2014). "For example, syndecan-2 and syndecan-4, as well as glypican-1, are overexpressed in breast cancer cell lines, compared to normal mammary cells, and are mediators of growth factor signaling." (PMID 23984412, 2013). "Therefore, we first analyzed the expression of SDC2 mRNA and protein in breast carcinoma tissues using the UALCAN online database with respect to the matched normal tissues." (PMID 40940401, 2025). "This may suggest that during the progression of breast cancer, SDC2 and FN expressions can be shifted from tumor tissues to MV-enriched EVs." (PMID 40940401, 2025). "It has been shown that SDC2 is another attractive target in breast cancer." (PMID 36980680, 2023). "Additionally, inhibiting SDC2 expression in MDA‐MB‐231 breast cancer cells (BCCs) reduced tumour volumes and improved survival in an adoptive transfer mouse model of breast cancer." (PMID 33152121, 2021). "SDC2 is a member of the syndecan family and has been reported to play a critical role either as a tumor suppressor, such as in osteosarcoma, or as an oncogene, such as in breast cancer." (PMID 35004840, 2021). "SDC2 is involved in the tissue development and homeostasis, but its overexpression has also been described in various types of cancers, including breast cancer, favoring a more aggressive phenotype by the inhibition of apoptosis and promotion of cell migration, invasion, and metastasis." (PMID 33014430, 2020). "Furthermore, Syndecan-2 and Syndecan-4 seem to be important regulators of breast carcinoma progression." (PMID 30922347, 2019). "To determine whether syndecan-2 and caveolin-2 expression correlates with disease and clinical outcome in breast cancer patients, we performed immunohistochemical analysis of human breast tissue microarrays." (PMID 25623282, 2015). "Finally, both syndecan-2 and caveolin-2 were upregulated in tissue arrays from breast cancer patients compared to normal mammary tissue." (PMID 25623282, 2015). "Cell surface proteoglycans, notably syndecan-2, may be important regulators of breast carcinoma progression through regulation of cytoskeleton, cell adhesion and invasion." (PMID 25623282, 2015).